STAT3 (signal transducer and activator of transcription 3)
Diseases named in the same sentence as STAT3 in open-access papers (continued):
Sharing a sentence is not in itself a finding about the gene and the disease.
melanoma (continued). "The gene expression profiles in the melanoma cell lines for AKT and STAT3 were heterogenous, whereby AKT as well as STAT3 gene expression were most effectively downregulated using the highest GP-2250 doses." (PMID 37895015, 2023). "Considering the constitutive and high levels of NLRP3 and of IL-1α in melanoma, we investigated the effects of NLRP3 inhibition on STAT3 activity and its phosphorylation." (PMID 36672229, 2023). "In contrast, inhibiting STAT3 by specific inhibitors or STAT3 siRNA decreases the levels of IL-6, IL-10, and VEGF mRNA expression in melanoma cells." (PMID 36979654, 2023). "In melanoma, sEV‐miR‐155 induces the proangiogenic switch of CAFs by inhibiting SOCS1 expression and activating the JAK2/STAT3 signaling pathway." (PMID 37171030, 2023). "Mechanistically, BET inhibitors sensitize melanoma cells to sunitinib by inhibiting the BRD4/GDF15 axis and BRD4/IL6/STAT3/GDF15 axis." (PMID 36720918, 2023). "Mechanistically, BET inhibitors sensitize melanoma cells to sunitinib by inhibiting the BRD4/GDF15 axis and the BRD4/IL6/STAT3/GDF15 axis." (PMID 36720918, 2023). "The gene expression profiles in melanoma cell lines for AKT and STAT3 were heterogeneous, whereas the downregulation of AKT as well as STAT3 gene expression was most effectively downregulated using GP-2250 doses of 500 μmol/L." (PMID 37895015, 2023). "In melanoma patients, the signal transducer and activator of transcription 3 (STAT3), which is known to antagonize MITF expression, has been found to play a role in melanoma ICD." (PMID 37626741, 2023). "Six STAT3-inducing cytokines (IL-6, IL-11, MIF, PDGF-AA, OPN, and MCP-1), all expressed by melanoma, were tested for their ability to induce these alterations in microglia cells." (PMID 37296634, 2023). "By contrast, the gene expression profiles in the melanoma cell lines for AKT and STAT3 were heterogeneous, whereas the downregulation of AKT as well as STAT3 gene expression was most effectively downregulated using the highest GP-2250 doses." (PMID 37895015, 2023). "The transcriptomic profiles of melanoma and microglia cells were compared to determine differences in the JAK1/STAT3 signaling pathway." (PMID 37296634, 2023). "In another study, the delivery of STAT3 siRNA into B16.F10 melanoma cells by polyplexes made of oleic acid- and stearic acid-modified polyethylenimine (PEI- p-STAT3-siRNA) decreased STAT3 expression." (PMID 38067351, 2023). "The downregulation of STAT3-targeted genes MCL-1, MMP-2, MMP-9, and VEGF, which promote cell growth, migration, and invasion, have been identified in melanoma cells after quercetin treatment." (PMID 36829966, 2023). "In murine melanoma B16F10 cells, apigenin decreased STAT3 phosphorylation and STAT3 nuclear localization resulting in the suppression of STAT3 transcriptional activity." (PMID 37687080, 2023). "Cationic liposomes containing STAT3 siRNA and curcumin were administered to the B16F10 melanoma cells." (PMID 38067351, 2023). "In the murine melanoma B16F10 cell line, apigenin effectively suppresses STAT3 phosphorylation, decreases STAT3 nuclear localization, and inhibits STAT3 transcriptional activity." (PMID 38203418, 2023). "STAT3 siRNA delivered by PEI vehicles effectively silenced STAT3 and inhibited melanoma cell proliferation in contrast with the application of naked STAT3 siRNA." (PMID 38067351, 2023). "Stattic, an inhibitor of STAT3, which is reported to impede the phosphorylation of STAT3, sensitized both A375 and SK-MEL-28 melanoma cells to sunitinib." (PMID 36720918, 2023). "As was observed for melanoma cells, IFNγ treatment of Ptpn2 knockout CT26 and MC38 cells enhanced the expression of the IFNγ response genes Cxcl1, Ccl5, Stat1, Stat2, Stat3, Irf1, Pd-l1, Tap1, and Casp8, compared with IFNγ-treated control cells." (PMID 36968224, 2023).
melanoma (continued). "Nevertheless, melanoma expresses high NLRP3-derived IL-1β expression, which specifically induces pSTAT3 and amplifies IL-6 secretion through the IL-1β/IL-6/STAT3 axis in vivo, leading to a further expansion of MDSCs." (PMID 36911674, 2023). "In the study of melanoma, several reports have demonstrated that the activation of EGFR/STAT3 signaling promotes the malignant progression of melanoma." (PMID 37944197, 2023). "Although raised from different cells, mastocytosis and melanoma share factors such as MITF, STAT3, and dependence on KIT signaling, suggesting some similarities in both pathologies." (PMID 36834926, 2023). "The findings of this study are also in agreement with previous findings in which TQ treatment reduced the phosphorylation of JAK2 and STAT3, which consequently led to enhanced apoptosis in SK-MEL-28 melanoma cells." (PMID 37375831, 2023). "In particular, the most studied and commonly altered pathways in melanoma are the mitogen-activated protein kinase (MAPK), PI3K, and Janus kinase-2/signal transducer and activator of transcription 3 (JAK-2/STAT3)." (PMID 35203404, 2022). "Treatment of A375 melanoma cells with 3, 5 DCPBC for 4 and 18 h profoundly suppressed phosphorylation of critical targets like EGFR, SRC, STAT3, JNK1/2, and MSK." (PMID 35208960, 2022). "Similar results were observed with artesunate-dependent inhibition of STAT3 in AML, diffuse large B cell lymphoma and melanoma cell lines." (PMID 36700235, 2022). "Mechanistically, we demonstrated that EEF2K upregulates the phosphorylation of STAT3 (p‐STAT3) at Tyr705, which binds to the promoter region of SPP1 and enhances its transcription, thus facilitating melanoma progression." (PMID 35184394, 2022). "After silencing STAT3 with siRNA, as indicated by a decrease in STAT3 and p‐STAT3, SPP1 was significantly decreased even in EEF2K‐overexpressing melanoma cells." (PMID 35184394, 2022). "Elevated DNAM-1 levels upon Stat3 deletion contribute to enhanced killing of DNAM-1 ligand-expressing tumor cells, e.g. B16F10 melanoma cells." (PMID 35865518, 2022). "Transfection‐induced re‐expression of SPP1 partly negated the inhibitory effect of EEF2K silencing on melanoma, whereas inhibition of SPP1 or STAT3 significantly abolished the efficacy of EEF2K on melanoma cells." (PMID 35184394, 2022). "Vanillic acid was found to reduce tumour growth through the STAT3 and p38 MAPK signalling pathways in melanoma-cell-bearing mice." (PMID 36678509, 2022). "In melanoma, inhibition of the SRC/STAT3 pathway reduces the expression of VEGF and matrix metalloproteinase-9, resulting in an anti-angiogenic effect." (PMID 36291659, 2022). "Consistently, based on TCGA datasets, STAT3 was positively correlated with SPP1 in multiple types of cancer, including melanoma." (PMID 35184394, 2022). "By analysis of SKCM-TCGA data, we also found a positive correlation between STAT3 and GZMB expression in human melanoma." (PMID 35145233, 2022). "In melanoma, the anti-tumor activity of brevilin A also depends on the status of JAK2/STAT3 pathway." (PMID 35818076, 2022). "We further analyzed the status of phospho-STAT3, a major transcription factor that stays downstream of the RAF pathway and is involved in maintaining cell proliferation and survival in melanoma." (PMID 35756619, 2022). "Consistently, the activation of STAT3 has been shown to be crucial for restricting the recruitment and activation of CD8+ T cells that are required to prevent the progression of melanoma." (PMID 36010693, 2022). "Evidence suggests that STAT3 can suppress expression of MITF, which is one of the main factors driving melanoma proliferation and differentiation." (PMID 35903898, 2022). "The examination of the TCGA data, IHC results, and melanoma gene profiles in our study demonstrated a strong relationship among Tim-3 (HAVCR2), PD1 (PDCD1), and STAT3 expression." (PMID 33936081, 2021).
melanoma (continued). "We used the transcriptomic and clinical data from melanoma and glioblastoma patients of anti-PD1 or anti-CTLA4 therapy to predict the immunotherapy response of cohorts with different STAT3/CDK2/4/6 expression." (PMID 33668805, 2021). "We highlighted a connection between mTORC2/RICTOR and STAT3 in resistant cells and revealed an interaction between RAS and RICTOR in resistant melanoma, which, when disrupted, impeded the proliferation of resistant cells." (PMID 34680615, 2021). "After that, melanoma cells were pretreated with LY294002, an AKT pathway inhibitor, or SH-4-54, a STAT3 pathway inhibitor, and then transfected with TRIM14 overexpression plasmid." (PMID 33982666, 2021). "Our study provides evidence that the STAT3 pathway behaves as an immune mediator, increasing Tim-3 expression in the TME and affecting the response to anti-PD-1 treatment in melanoma." (PMID 33936081, 2021). "Together, these results suggest that Lrg1 promotes melanoma cell migration and invasion by activating the EGFR/STAT3 signalling pathway in a Src-independent manner." (PMID 34208965, 2021). "IL-6 was known to activate STAT3 and consequently increase MMP-2 expression and the metastatic ability of cancer cells in malignant melanoma." (PMID 34267603, 2021). "Bhandarkar and colleagues demonstrated that Tris DBA can reduce melanoma cell proliferation by inhibiting the activation of MAPK, Akt, STAT3, and phospho-S6 kinase, and downregulated the expression of N-myristoyltransferase-1." (PMID 34771643, 2021). "Specifically, it was found that elevated S100B in malignant melanoma cells blocks CREB phosphorylation and inhibits IL6/STAT3-signaling." (PMID 34411141, 2021). "TRIM14 was upregulated in melanoma cell lines to promote melanoma cell proliferation, clone formation, migration, invasion, and epithelial-mesenchymal transition through PI3K/AKT and STAT3 pathways." (PMID 33982666, 2021). "To confirm the role of combination STAT3 downregulation and anti-PD-1 treatment on CD8+ T cells, we analyzed the cell phenotype and cytokine expression pattern of CD8+ T cells in melanoma." (PMID 33936081, 2021). "Using a mouse model of melanoma, we report here that NLRP3 activation induces IL‐1β-mediated IL‐6 production resulting in STAT3 activation." (PMID 34531850, 2021). "In melanoma, the lncRNA LHFPL3-AS1 is transcriptionally activated by STAT3 and further enhances STAT3 expression via sponging miR-580-3p to activate JAK2/STAT3 signaling." (PMID 34414175, 2021). "Collectively, the present study offers us a new horizon to better understand the role of lncRNAs in melanoma pathogenesis and demonstrates that CD27-AS1-208 up-regulation contributes to melanoma progression by activating STAT3 pathway." (PMID 35096622, 2021). "The results showed that enforced PEAK1 expression facilitated melanoma cell growth, invasion and metastasis via activating JAK/STAT3 signals, and PEAK1 knockdown inhibited melanoma cell growth, invasion and metastasis via inactivating JAK/STAT3 signals." (PMID 34365903, 2021). "In human melanoma cells, the pan-JAK inhibitor 6BIO can effectively induce tumor cell apoptosis by inhibiting JAK/STAT3 signaling." (PMID 34365903, 2021). "For example, melanoma cell-secreted exosomal miR-155-5p, which was selected as a survival-associated miRNA, could induce a proangiogenic switch of fibroblasts associated with cancer through improving proangiogenic factors' expression in recipient fibroblasts via SOCS1/JAK2/STAT3 signaling pathway." (PMID 33897771, 2021). "Overall, our study provided strong evidence of Lrg1’s role in melanoma metastasis and Lrg1 exerting its function through activation of the EGFR/STAT3 signalling pathway." (PMID 34208965, 2021). "ABL1 promotes melanoma invasion through STAT3-dependent MMP1 expression, while ABL2 promotes melanoma invasion by increased expression of MMP-1, MMP-3, and MT1-MMP independently of STAT3." (PMID 34022881, 2021).
melanoma (continued). "OSM is a cytokine belonging to the IL-6 family, and in the A375 human melanoma cell line, OSM receptor signaling is mediated by JAK1, JAK2, and tyrosine kinase 2 signaling via STAT3 and STAT5b." (PMID 34067095, 2021). "We also found that targeting JAK/STAT3 signaling reversed PEAK1-induced effects, which provided a novel therapeutic target for melanoma." (PMID 34365903, 2021). "Here, the use of carbon ion beams (5 GyE) for melanoma-bearing mice was found to reduce the population of MDSC in the bone marrow, peripheral blood, and spleen of the animals via a JAK2/STAT3-dependent mechanism." (PMID 34732697, 2021). "Knockdown of TRIM14 suppressed melanoma cell proliferation, invasion, and epithelial-mesenchymal transition through PI3K/AKT and STAT3 pathways." (PMID 33982666, 2021). "Results showed that in the murine melanoma B16F10 cell line, API (150 mg/kg) presented antimetastatic activity by suppressing STAT3 phosphorylation and downregulating MMP-2, MMP-9, and VEGF pathways." (PMID 34239802, 2021). "STAT3 activation can be induced by the upstream tyrosine kinases Src and JAK, whose inhibition blocks STAT3 signaling activation in melanoma." (PMID 34277607, 2021). "Our further wound healing assay showed that TRIM14 overexpression promoted the migration of melanoma cells, while inhibition of AKT or STAT3 pathway with specific inhibitors partially abolished the migration of melanoma cells induced by TRIM14 overexpression." (PMID 33982666, 2021). "These are EGFR, ERRFI1, IL6, JAK2, PLXNC1, RGL3 which were found to be upregulated and CBL, CDC42, PIK3R3, STAT3, UBE2D2 and YWHAZ which were found to be downregulated; Melanoma has PLXNC1 as upregulated and TGFA as downregulated gene." (PMID 34764329, 2021). "Vitreous fluid of eyes with melanoma was shown previously to contain an elevated level of IL-6 (along with other cytokines/chemokines) compared to the healthy counterparts, suggesting that—via the prolonged activation of STAT3—it may contribute to the formation and maintenance of these tumors." (PMID 34884773, 2021). "The combination of PLB and celecoxib decreased melanoma cell proliferation and retarded vascular development of tumors mediated by inhibition of COX-2 and STAT3 leading to decreased levels of key cyclins key on which melanoma cells were dependent for survival." (PMID 33344645, 2020). "In melanoma cells, the STAT3 signaling pathway can promote MMP2 expression, while inhibition of phosphorylated STAT3 expression can significantly inhibit MMP2 expression in vivo, which inhibits tumor cell growth and invasion." (PMID 33330321, 2020). "In melanoma, CXCL8 expression can be regulated by nuclear factor of activated T-cells 1 (NFAT1), signal transducer and activator of transcription 3 (STAT3) and WNT signaling pathway." (PMID 32466509, 2020). "Adding recombinant IL-6 to melanoma cells reversed those in vitro and in vivo effects, suggesting that ATF3 expression by HDFs regulates melanoma progression through the IL-6/STAT3 pathway." (PMID 32373541, 2020). "It is postulated that this process is one of the main reasons for the aggressiveness of human malignant melanoma and it has been shown that the transcription factors TWIST, ZEB1 and STAT3 are its main drivers." (PMID 32899370, 2020). "Apart from STAT3, MAPK, and AKT signaling cascades are also constantly activated and promote melanoma progression." (PMID 32536866, 2020). "Treatment of melanoma cell lines with hepatocyte growth factor (HGF), the ligand for the c-MET receptor, led to increased levels of phosphorylated STAT3 in two of three parental lines tested (MM455 and MM603)." (PMID 32632141, 2020). "Further study showed that shikonin decreased the levels of STAT3-targeted genes Mcl-1, Bcl-2, MMP-2, vimentin, and Twist, which are involved in melanoma survival, migration, and invasion." (PMID 32536866, 2020).
melanoma (continued). "In agreement with the previous studies, we found that phosphorylation of STAT3 in both Mel-JuSo and UACC62 melanoma cells decreased dramatically after culture with CM derived from ATF3-overexpressing HDFs." (PMID 32373541, 2020). "Collectively, the positive correlation together with the high levels of TLR4 expression and STAT3 phosphorylation in human melanoma tissues suggests a link between TLR4 and STAT3 in melanoma pathogenesis." (PMID 32312954, 2020). "Collectively, our work identifies STAT3 activation as a key event in TLR4 signaling-mediated melanoma progression, shedding new light on the pathophysiology of melanoma." (PMID 32312954, 2020). "It has been reported that NT157 inhibits proliferation in the RAF inhibitor resistant melanoma cell line A375, both through reduced IGF1-signaling and reduced STAT3-signaling." (PMID 32667922, 2020). "Our study also demonstrated that the effects of BEA and BEA G1 are associated with the suppression of molecular targets, which play crucial roles in melanoma oncogenesis, including ERK, JNK, p38, NF-κB, STAT3, and MITF." (PMID 32340351, 2020). "Further analyses showed that TLR4 expression and STAT3 phosphorylation were positively correlated in the 208 samples, especially in early-stage (T1N0M0) melanomas (samples C4, D9, F2, F9, G9, H8, H9)." (PMID 32312954, 2020). "Such a scenario poses limitations to the straightforward inhibition of either STAT3 or STAT5 in NK cells and necessitates elucidating how the STAT3/STAT5 ratio is regulated and what is its contribution to the melanoma–NK cells interplay." (PMID 31569642, 2019). "In the current study, we established that STAT3 is constitutively bound to the PDK1 promoter and promotes PDK1 transcription in melanoma through at least two STAT3 responsive elements." (PMID 30622697, 2019). "Herein, we review the current knowledge of the effects of STAT3 and STAT5 signaling in melanoma, inflammation, and autoimmune disorders and estimate their value for concurrent management of these interconnected conditions." (PMID 31569642, 2019). "During experiments addressing STAT3’s role in tumorigenesis, we observed that SW1 mouse melanoma cells transduced with STAT3β presented a marked reduction in the levels of PKC phosphorylated at the hydrophobic motif (Ser660 in PKCβII)." (PMID 30622697, 2019). "STAT3/STAT5-related inflammatory and autoimmune diseases with a still understudied effect on melanoma incidence are also mentioned (Section 6.9, Section 6.10, Section 6.11 and Section 6.12)." (PMID 31569642, 2019). "Our goal was to characterize the precise mechanism linking STAT3 with the activity of Akt and other AGC kinases in cancer using melanoma cells as a model." (PMID 30622697, 2019). "We next investigated the effects of STAT3 inhibition on NDV/FMW replication and cell death in melanoma cells." (PMID 31192135, 2019). "STAT3 is the best-studied family member of the JAK-STAT pathway in cancer, and is a known oncogene in various types of solid malignancies, like melanoma or lung cancer." (PMID 31817042, 2019). "We show that PDK1 is a transcriptional target of STAT3, linking STAT3 pathway with AGC kinases activity in melanoma." (PMID 30622697, 2019). "STAT3 and/or STAT5 cascades are commonly activated during melanoma progression and mediate the metastatic effects of key oncogenic factors." (PMID 31569642, 2019). "The close relationship between G6PD and NOX4 maintains ROS homeostasis and promotes downstream redox signaling, including STAT3, c-SRC and SHP2, in melanoma cells." (PMID 31500396, 2019). "Recent pieces of evidence have shown that STAT3 activation is an important mechanism of resistance to targeted therapies against mutant BRAF, a critical oncogene in melanoma." (PMID 30622697, 2019). "Our previous work showed that targeting STAT3 can inhibit tumor VEGF expression and angiogenesis in melanoma cells." (PMID 31192135, 2019).